NXPH4 (neurexophilin 4)
Diseases named in the same sentence as NXPH4 in open-access papers (continued):
Sharing a sentence is not in itself a finding about the gene and the disease.
cancer (11 papers, 2017 to 2025). A tumor composed of atypical neoplastic, often pleomorphic cells that invade other tissues. "NXPH4 expression in pan-cancer is substantially linked to immune cell infiltration in the immune microenvironment." (PMID 38613793, 2024). "By correlating NXPH4 with immune cells in the tumor microenvironment, it was observed that NXPH4 was linked to different immune cell infiltrations in various cancers." (PMID 38613793, 2024). "To uncover the mechanisms underlying NXPH4-induced cancer progression, we analyzed associations between NXPH4 expression and pathway scores using the TCGA database." (PMID 39164641, 2024). "In conclusion, this study revealed the dysregulation of NXPH4 at a pan-cancer level and suggested the potential of NXPH4 as a diagnostic and prognostic biomarker for certain cancer." (PMID 38613793, 2024). "High expression of NXPH4 in pan-cancer might be associated with the increase in copy number and hypomethylation." (PMID 38613793, 2024). "NXPH4 is upregulated in most cancers and has a high diagnostic value." (PMID 38613793, 2024). "Dysregulation of NXPH4 expression in some cancers may be associated with abnormal copy number variation and methylation." (PMID 38613793, 2024). "The heat maps displayed the association between NXPH4 expression and immune inhibitors in cancers." (PMID 36245978, 2022). "In addition, NXPH4 is associated with poorer prognosis in many cancers and could be used as a prognostic marker." (PMID 38613793, 2024). "This study comprehensively analyzed the abnormal expression, copy number variation, methylation, and prognostic value of NXPH4 in pan-cancer, including a combined comparative analysis of 33 cancers downloaded from TCGA and GTEx databases." (PMID 38613793, 2024). "Subsequently, a functional enrichment analysis of NXPH4 in each cancer at the single-cell level was performed using the CancerSEA database." (PMID 38613793, 2024). "This study investigated the expression level, diagnostic value, copy number variation, methylation, prognostic value, and immunological relevance of NXPH4 on pan-cancer." (PMID 38613793, 2024). "In most cancers, NXPH4 exhibited a positive link to follicular helper T cells, M0 macrophages, and plasma cells, and a negative link to CD8+ T cells, CD4+ memory T cells, and monocytes." (PMID 38613793, 2024). "Although NXPH4 has excellent potential in cancer diagnosis and prognosis, its molecular function is still poorly understood." (PMID 38613793, 2024). "On the other hand, ectopic expression of NXPH4 contributed to an accelerated rate of DNA replication in the investigated cancer cells." (PMID 39164641, 2024). "Our findings, together with the previous studies, suggest that NXPH4 acts as an oncogene to promote cancer development in various settings." (PMID 38613793, 2024). "NXPH4 overexpression was further determined by assessing its expression between the adjacent and cancer tissues using the GSE37182 and GSE83889 datasets from the GEO database." (PMID 39164641, 2024). "Our study also found that NXPH4 has the potential to differentiate between cancerous and paraneoplastic tissues in 12 types of cancers, including LIHC." (PMID 38613793, 2024). "NXPH4 promotes cancer cell proliferation, migration, and invasion and is vital in the tumor metastasis cascade." (PMID 38613793, 2024). "The CIBERSORT and TIMER algorithms were utilized to evaluate the link between NXPH4 and the abundance of individual immune cell types across various cancer types (pan-cancer analysis)." (PMID 38613793, 2024). "In BLCA, NXPH4 promoted cancer cell proliferation and metastasis in vitro and induced gemcitabine resistance in BLCA, partly by enhancing glycolytic activation." (PMID 38613793, 2024). "It was shown that the expression of NXPH4 was obviously elevated in tumor tissues in comparison with their para-cancer counterparts, normal bladder (NB) tissues." (PMID 35954445, 2022).
cancer (continued). "These heat map results displayed that NXPH4 expression was related with chemokines and chemokine receptors in cancers." (PMID 36245978, 2022). "At the same time, NXPH4 increased more significantly in cancer compared to adjacent tissues (P < 0.05); NXPH4 was further verified in human paraffin sections with results showing that its expression was significantly increased in tumor tissues." (PMID 36245981, 2022). "Recent studies have shown that NXPH family member 4 (NXPH4) plays an important role in the progression of cancer." (PMID 35758021, 2022). "Therefore, further experiments were conducted, which aimed at exploring the NXPH4 expression levels in other cancers and the potential mechanisms of high expression using bioinformatics." (PMID 38613793, 2024). "In addition, the current research analyzed the methylation levels and copy number variation of NXPH4 in an attempt to explain the possible mechanisms of its dysregulation in some cancers." (PMID 38613793, 2024). "Our study also revealed a higher NXPH4 expression level in the transcriptome of most cancers." (PMID 38613793, 2024). "The role of NXPH4 in cancer has only recently been investigated." (PMID 38613793, 2024). "We first examined the expression of NXPH4 in pan-cancer, and then focused on BCa." (PMID 35758021, 2022). "Our findings also showed that the mRNA expression levels of NXPH4 were higher in cancer tissues." (PMID 35758021, 2022). "Currently, the role of NXPH4 in cancer has attracted attention of some researchers." (PMID 36245978, 2022). "It showed that NXPH4 expression was abnormally expressed across different cancer types." (PMID 35758021, 2022). "Currently, only a few research has reported the function of NXPH4 in cancers." (PMID 36245978, 2022). "Specially, NXPH4 is gradually being discovered for its pro-cancer role." (PMID 35758021, 2022). "This suggests that NXPH4 may be an oncogene in some kinds of tumors while it may prevent the occurrence of tumor cells in other kinds of cancers." (PMID 35954445, 2022). "We estimated the expression status of NXPH4 in pan-cancers using TIMER database." (PMID 36245978, 2022). "However, in LIHC, NXPH4 exhibited a positive link to CD4+ T cells, neutrophils, macrophages, and B cells, suggesting that NXPH4 may have different immune effects in various cancers." (PMID 38613793, 2024). "The findings of this research validate previous research and analyze the link between NXPH4 and OS, DSS, and PFS in pan-cancer." (PMID 38613793, 2024). "This research demonstrates elevated levels of NXPH4 in CRC and HCC contribute to cancer cell proliferation, growth, and metastasis, underscoring its role in tumor progression." (PMID 39164641, 2024). "In Non-small Cell Lung Cancer (NSCLC), NXPH4 is regulated by its upstream transcription factor E2H2, which promotes cancer cell proliferation and invasion by altering the structure of CDKN2A." (PMID 38613793, 2024). "Differentially methylated CpGs related to NXPH4 and LBX2 have previously been described in a study that developed a placental epigenetic clock, whereas aberrant methylation and/or expression of NXPH4, EPS8L2, AMOTL1, IRX2, and LBX2 have also been described in multiple types of cancers." (PMID 40338255, 2025). "The outcomes from the CIBERSORT analysis highlighted that NXPH4 demonstrated a positive link to follicular helper T cells, M0 macrophages, and plasma cells while showing a negative correlation with CD8+ T cells, CD4+ memory T cells, and monocytes in most cancers." (PMID 38613793, 2024). "Finally, we created a receiver operating characteristic curve to judge whether NXPH4 could be used as a biomarker to distinguish between the normal bladder and cancer tissues." (PMID 35954445, 2022). "TIMER algorithm results showed that NXPH4 exhibited a negative link to CD8+ T-cells, CD4+ T-cells, neutrophils, macrophages, and B-cells in most cancers." (PMID 38613793, 2024).
tumor (10 papers, 2022 to 2026). "Our findings revealed considerable associations between NXPH4 expression and multiple signaling pathways, encompassing angiogenesis, tumor proliferation, DNA replication, the epithelial–mesenchymal transition (EMT) process, and hypoxia." (PMID 39164641, 2024). "Mutations in the FGFR3 gene are associated with low PD-L1 expression in BC, high expression of MAN1B1 is related to poor prognosis, high expression of COL6A1 in tumor cells promotes tumor growth and metastasis, and high expression of NXPH4 is associated with poor prognosis in BC." (PMID 39559360, 2024). "The significant upregulation of NXPH4 expression in tumor tissues was linked to poor prognosis." (PMID 39164641, 2024). "Consequently, NXPH4 could provide a prognostic indicator of OS in BCa as it is associated with immunity and promotes tumor growth." (PMID 35758021, 2022). "The mouse subcutaneous tumor model also showed that HIF1A exhibited reduced expression level after NXPH4 knockdown." (PMID 39164641, 2024). "The outcomes demonstrated that the removal of m5C modifications from native NXPH4 mRNA severely impeded the capacity of tumor cells to proliferate, migrate, and invade." (PMID 39164641, 2024). "We conducted GSEA analyses and the result indicate that the expression of NXPH4 promotes the glycolysis of tumor cells." (PMID 35954445, 2022). "For in vitro experiments, we focused on the function of NXPH4 in BCa and demonstrated that cell proliferation and colony formation were significantly inhibited after knocking down NXPH4, implying that NXPH4 has a tumor-promoting effect." (PMID 35758021, 2022). "To further explore the relationship between NXPH4 expression and tumor immunity, we used CIBERSORT calculation to determine the proportion of 22 immune cells infiltrating in the tissues of each BCa patient." (PMID 35758021, 2022). "In agreement with bioinformatic analysis, we confirmed that NXPH4 acts a tumor-promotion role in BCa and the proliferation of BCa cells were significantly inhibited after knockdown of NXPH4." (PMID 35758021, 2022). "The immunohistochemistry results suggested that the expression of NXPH4 was significantly elevated in tumor tissue specimens." (PMID 35758021, 2022). "The result displayed that the methylation level of NXPH4 was lower in tumor samples as compared to normal samples, but the difference was not significant (p = 0.145)." (PMID 36245978, 2022). "According to the RNA-seq data of the GTEx and TCGA databases, the expression of NXPH4 mRNA in 19 types of tumor tissues (including BCa tissues) were significantly higher than those in normal tissues." (PMID 35758021, 2022). "This suggests that NXPH4 may be an oncogene in several types of tumors and may prevent tumor cell genesis in other types of tumors." (PMID 38613793, 2024). "Conversely, overexpressing NXPH4 significantly enhanced organoid growth, and these findings were validated in vivo by implanting cells with stable NXPH4 downregulation subcutaneously, thereby confirming our earlier observation of reduced tumor cell proliferation upon NXPH4 silencing." (PMID 39164641, 2024). "TCGA data analysis revealed elevated NXPH4 expression in tumors with advanced T and N classifications, as well as higher tumor grade in both CRC and HCC, highlighting NXPH4’s strong correlation with unfavorable prognosis in CRC and its association with OS and DSS in HCC." (PMID 39164641, 2024). "Collectively, our findings strongly support NXPH4 as a tumor-promoting gene in both CRC and HCC." (PMID 39164641, 2024). "Additionally, the upregulation and downregulation of NXPH4 in tumor cells also promote and inhibit cell proliferation, respectively." (PMID 38613793, 2024). "NXPH4, regulated by m5C, promotes malignant tumor progression and regulates the HIF pathway." (PMID 39164641, 2024).
tumor (continued). "It is consistent with the results of this study, and this study shows that NXPH4 not only has the ability to promote tumorigenesis but also may have certain value in tumor immune regulation." (PMID 36245981, 2022). "We speculated that the upregulated NXPH4 expression may suppress the migration of immune cells to tumor microenvironment, which may partially interpret how NXPH4 impact immune cell infiltration in HCC." (PMID 36245978, 2022). "Notably, the combination of NXPH4 knockdown and enzalutamide treatment showed potent synergistic effects, significantly suppressing cell proliferation in vitro and substantially inhibiting tumor growth in vivo." (PMID 41639054, 2026). "In addition to its ability to promote tumourigenesis, NXPH4 may also be significant in tumor immunomodulation." (PMID 38613793, 2024). "Furthermore, findings from the colony formation assay underscored that NXPH4 knockdown decreased the clonogenic capacity of tumor cells, whereas the counterpart assay revealed an increased number of colonies in cells overexpressing NXPH4 compared to the control group." (PMID 39164641, 2024). "Therefore, we speculated that NXPH4 could regulate tumor immune cell infiltration, but different tumors may have different types of immune cells." (PMID 36245978, 2022). "Our results not only provide a selection basis for clinical personalized therapy, especially immunotherapy, but also provide a new molecular target for molecular therapy and further analyzed and verified the gene NXPH4 that may play a role in tumor immune progression." (PMID 36245981, 2022). "Therefore, our research conducted a CCK-8 assay, wound scratch assay, and transwell invasion assay to judge whether NXPH4 influences these abilities of tumor cells." (PMID 35954445, 2022). "In summary, we identified NXPH4 as a novel prognostic biomarker and a gene that promotes CRC and HCC tumor progression." (PMID 39164641, 2024). "This suggests that NXPH4 may be associated with the immunosuppressive tumor microenvironment (TME); however, there are currently no reports on the impact of NXPH4 on the TME of tumors, and detailed mechanisms still require further functional experiments to be determined." (PMID 38613793, 2024). "We found that the expression of NXPH4 and NDUFA4L2 and the level of glycolysis have a great influence on the tumor size and tumor weight originating in mice, which is consistent with the theory proven in vitro." (PMID 35954445, 2022). "Among them, NXPH4 and ABCA4, as the genes with the heaviest regression coefficient, both suggest a worse prognosis, and NXPH4 is also significantly increased in MIBC tumor tissues." (PMID 36245981, 2022). "Also, the same study with human cell lines observed that a higher expression of NXPH4 is related to immune cell infiltration in HCC, indicating a role in tumor microenvironment modulation." (PMID 40489480, 2025). "We used a comprehensive approach, considering genes correlated with NXPH4 expression in CRC and HCC, genes associated with OS in CRC, and genes demonstrating a two-fold differential expression between tumor and non-tumor tissues in CRC." (PMID 39164641, 2024). "Our findings provide insights into the tumor-promoting effects of NXPH4 in CRC and HCC, highlighting how RNA modifications might influence NXPH4 mRNA to evade RNautophagy and consequently elevate NXPH4 expression." (PMID 39164641, 2024). "Therefore, we conducted an integrated bioinformatic analysis for NXPH4 expression in HCC in multiple databases, including The Cancer Genome Atlas (TCGA), International Cancer Genome Consortium (ICGC), Gene Expression Omnibus (GEO), and Tumor Immunity Estimation Resource (TIMER)." (PMID 36245978, 2022).
NXPH4 also shares sentences with these, for which no sentence is quoted: bladder urothelial carcinoma (2 papers); cervical squamous cell carcinoma (2); cholangiocarcinoma (2); gastric cancer (2); head and neck squamous cell carcinoma (2); acute myeloid leukemia (1); colon adenocarcinoma (1); endocervical adenocarcinoma (1); infection (1); kidney chromophobe (1); lung adenocarcinoma (1); metabolic syndrome (1); prostate adenocarcinoma (1); prostate carcinoma (1); Skin Cutaneous Melanoma (1); thymoma (1); uveal melanoma (1).